IL6 (interleukin 6)
Diseases named in the same sentence as IL6 in open-access papers (continued):
Sharing a sentence is not in itself a finding about the gene and the disease.
colitis (continued). "After the onset of colitis, IL-10−/− mice have a higher secretion of inflammatory cytokines than wild-type mice, including TNF-α, IL-1β, IL-6, and IFN-γ." (PMID 40732952, 2025). "The present investigation observed notably elevated pro-inflammatory cytokine levels (TNF-α, IL-6, and IL-1β) in the colon of mice with DSS-induced colitis." (PMID 39699220, 2025). "Limonin reduced the generation of proinflammatory cytokines TNF-α, IL-1β, and IL-6 as well as the expression of inflammatory proteins COX-2 and iNOS in the colonic tissues of mice with DSS-induced colitis." (PMID 40078988, 2025). "Polysaccharides extracted from Ganoderma lucidum and Lentinula edodes demonstrate immunomodulatory effects in colitis models, promoting nitric oxide, tumor necrosis factor-alpha (TNF-α), and interleukin-6 (IL-6) production." (PMID 40427011, 2025). "Further ELISA and qRT-PCR results showed that the protein and mRNA levels of inflammatory factors IL1-β, IL6, G-CSF and CXCL1 in the colon tissue homogenates of KO colitis mice were significantly higher than those of WT mice." (PMID 41417165, 2025). "PPI analysis revealed that these compounds effectively modulate inflammatory pathways, particularly IL‐6 and TNF, with significant reductions observed in DSS‐induced colitis models." (PMID 41164267, 2025). "The combined administration of mesalamine and PTX produced the most pronounced effect, significantly reducing IL‐6 and STAT3 levels by 57.93% (F = 505.4, p < 0.0001) and 68.91% (F = 153.3, p < 0.0001), respectively, in comparison to the colitis group." (PMID 40387460, 2025). "In a colitis-induced model, Tyr reduces inflammation by activating the MAPK pathway and regulating the gene expression of IL-6, COX-2, and NF-κB." (PMID 40298838, 2025). "In contrast, the insufficient barrier function of IECs and microbial invasion increase the production of pro-inflammatory cytokines, including TNF-α, IFN-γ, and IL6, during intestinal inflammation in murine DSS-induced colitis and human UC and CAC." (PMID 39631567, 2025). "Pro-inflammatory cytokines (IL-1β, IL-6, TNF-α) were markedly elevated in the Colitis group, while anti-inflammatory IL-10 was suppressed (p < 0.01)." (PMID 40574090, 2025). "Arbutin has been reported to significantly down-regulate the levels of inflammatory cytokines (IL-1β, IL-6, and TNF-α), iNOS, and cyclooxygenase-2 (COX-2) in colitis mice." (PMID 40078988, 2025). "The results revealed a significant increase in the levels of inflammatory cytokines IL-6 and TNF-α in the colon tissue of DSS-induced colitis model mice (p < 0.001) compared with the control group." (PMID 40433374, 2025). "Animal experiments further demonstrate that PMS extracts reduce levels of pro‐inflammatory factors such as IL‐6 and TNF‐α in colitis models." (PMID 40289624, 2025). "In parallel with these findings, garlic-derived exosome-like nanovesicles suppressed IL-6, IL-1β, TNF-α, and IFN-γ levels, TLR4 and Myd88 pathways in LPS-treated Caco2 cells, and the dextran sulfate-treated mouse colitis model." (PMID 40149930, 2025). "DSS in mice appear to induce a clear interferon alpha and gamma response as well as an interleukin 6 (IL-6) and tumor necrosis factor alpha (TNF-a) response that is in line with the signatures typically observed in human colitis." (PMID 38249103, 2024). "SASP can reduce oxidative stress and the inflammatory response in TNBS-induced colitis model rats by reducing the expression of TNF-α and IL-1β and inhibiting IL-6/JAK2/STAT3 signal transduction." (PMID 39318778, 2024). "Anti-IL-6 combined with antibiotics increased the efficacy of anti-CTLA-4 and reduced colitis severity in Stat3Δ/Δ mice." (PMID 39247203, 2024). "We first investigated the relationship of miR146a expression to that of pro-inflammatory cytokines IL-6 and TNF in the colons of mice induced with TNBS colitis." (PMID 38786849, 2024).
colitis (continued). "Significantly higher levels of IL-6, IL-1β and TNF-α were detected in mice with colitis compared to control mice." (PMID 39165355, 2024). "Here, in the zebrafish colitis model, DSF treatment significantly inhibited the abnormal increase in the expression of pro-inflammatory cytokines (tnfa, il1b, and il6) and the decrease in the expression of the anti-inflammatory factor il10." (PMID 38892496, 2024). "The severity of the colitis was evaluated by body weight, colon length, DAI score, HE staining and expression of TNF-α and IL-6." (PMID 38243324, 2024). "Here, we evaluated the effects of Raf on inflammation using a DSS-induced colitis mouse model, focusing on serum levels of IL-2, IL-1β, TNF-α, and IL-6." (PMID 38928791, 2024). "Concentrations of the cytokines IL-23, IL-17, IL-6, TNF,and IL-1β were higher in the colon from the colitis group comparedto the control groups, confirming the presence of colitis." (PMID 39022369, 2024). "IFX and 1,25-dihydroxyvitamin D3 (VitD3) synergistically prevented the development of colitis by improving clinical signs, pathological and hematological manifestation, and inhibiting intestinal inflammation (decreasing TNF-α, IL-1β, and IL-6)." (PMID 39055880, 2024). "Several studies have suggested the anti-inflammatory functions of NA in various diseases, such as colitis and Parkinson's disease, especially in reducing the release of pro-inflammatory cytokines, such as TNF-α, IL-6 and NF-κB with therapeutic effects." (PMID 39364738, 2024). "In our experimental study, we observed a significant increase in the mRNA expression levels of pro-inflammatory cytokines, including IL-1β, IL-6, and TNF-α, following DSS administration, indicative of colitis induction in mice." (PMID 38760355, 2024). "Strains that induced higher levels of the anti-inflammatory cytokine IL-10 and lower levels of pro-inflammatory cytokines such as IL-1β, IL-6, interferon γ (IFNγ), and TNF-α offered protection in induced colitis." (PMID 39767038, 2024). "HFD feeding resulted in colitis: it elevated myeloperoxidase, TNF-α, IL-1β, and IL-6 levels, NF-κB activation (p-p65/p65), and NF-κB+CD11c+ cell number and decreased IL-10 and SIRT1 levels and AMPK activation (p-AMPK/AMPK) in the colon." (PMID 39599597, 2024). "The results showed that ZSS polysaccharide (20 mg/kg) significantly improved the severity of colitis in colitis rats and inhibited the inflammatory response by reducing the activity of TNF-α, IL-1β, IL-6 and MPO in colitis rats." (PMID 39679366, 2024). "Inflammatory cytokines and mediators such as IL-1β, IL-6, and TNF-α are pivotal in initiating and sustaining colitis." (PMID 39061864, 2024). "More importantly, combined SFELNVs and CX5461 alleviated mice colitis by inhibiting pro-inflammatory factors (TNF-α, IL-1β, and IL-6) expression and promoting M2 macrophage polarization." (PMID 39379937, 2024). "We revealed that LA exerted proinflammatory effect on macrophages, which increased the expression of IL‐6, and IL‐1β and decreased the expression of TGF‐β, inhibited Treg cell differentiation, and increased susceptivity to DSS‐induced colitis." (PMID 38477534, 2024). "In conclusion, targeting the NF-κB and MAPK signaling pathways to reduce the expression of inflammation-related genes and proteins, such as IL-6 and TNF-α, represents an effective strategy for treating colitis." (PMID 39323474, 2024). "EPS derived from lactobacillus have been shown to effectively reduce the levels of pro-inflammatory cytokines IL–1ß, IL–6, and TNF–α in colitis mice." (PMID 38731362, 2024). "Our research also confirms that XYKJP inhibits IL-6 expression and phosphorylation of JAK2 and STAT3, thereby reducing the inflammatory response to colitis." (PMID 39133435, 2024). "Treatment with SFN significantly reduced the concentrations of pro-inflammatory cytokines IL-6, IFN-γ and TNF-α in mice with DSS-induced colitis." (PMID 39517291, 2024).
colitis (continued). "Bifidobacterium adolescentis ameliorated DSS-induced colitis by reducing TNF-α, IL-1β, and IL-6 levels and increasing IL-10 and IL-4 levels." (PMID 38540864, 2024). "Astaxanthin significantly suppressed the mucosal mRNA expression of pro-inflammatory cytokines, including IL-1β, IL-6, TNF-α, IL-36α, IL-36γ, and COX-2, in DSS colitis." (PMID 38672464, 2024). "Five days after the induction of colitis, untreated TNBS mice demonstrated significantly increased relative gene expression of IL-6 in their colons compared to the controls (p = 0.004)." (PMID 38786849, 2024). "Specifically, the levels of TNF-α, IL-1β, IL-6, IL-10, IL-2, and IL-12 SOD, CAT, GSH-Px, and MDA were modulated in rats with colitis, also inhibiting TLR4/NF-κB pathway activation." (PMID 39494333, 2024). "An increased Nrf2 expression in the colorectal mucosa of mice along with a decreased expression of TNF-α, IL-1β, IL-6, IFN γ, NF-κB, COX2, and iNOS were also found after a 4 week supplementation with crocin in DSS-induced colitis." (PMID 38543230, 2024). "In experimental colitis models, histone deacetylase (HDAC) suppressed Th17 differentiation through the IL-6/STAT3/IL-17 pathway, thereby alleviating experimental colitis." (PMID 39020448, 2024). "As shown by immunohistochemistry staining and Western blot, THZ2 also reversed the promotion of COX-2, IL-6, β-catenin, and snail by DSS in the acute colitis mouse models." (PMID 38540292, 2024). "CPP1-2-1, on the other hand, reduces the expression of TLR4, NF-κB, TNF-α, and IL-6 in LPS-induced RAW264.7 cells in a dose-dependent manner and alleviates DSS-induced pathological injury in mice with colitis." (PMID 39202931, 2024). "They tested this concept using ELISA and discovered that IL-1β, IL-6, and TNF-α were significantly induced in the colon tissue of DSS-induced colitis mice, indicating a potent anti-inflammatory mechanism." (PMID 39323474, 2024). "The improvement of colitis after hesperidin treatment is related to the inhibition of pro-inflammatory cytokines TNF-α, IL-6, IL-1β, and IL-33 as well as NF-κB activation in the colon." (PMID 39494333, 2024). "The results demonstrated that SP decreased mRNA levels of IL-6, TNF-α, IL-17A, and IL-1β, but enhanced the mRNA level of IL-10 in mice with DSS-induced colitis." (PMID 38725846, 2024). "At the level of mRNA, the relative expression of TNFα, IL1β, IL6, MMP9, and PTGS2 increased significantly in DSS-induced colitis compared with the control group." (PMID 39064786, 2024). "We estimated the effect of XYKJP on inflammatory cytokines in colitis tissues and found that XYKJP treatment led to a reduction in the levels of IL-1β, TNF-α, and IL-6, and a significant improvement in the level of IL-10 and IL-22, as demonstrated by ELISA." (PMID 39133435, 2024). "S. cerevisiae strains exhibited in vivo reduction of pro-inflammatory cytokines IL-1β, IL-6 and TNF-α and promoted the expression of the anti-inflammatory cytokine IL-10 in colitis mice." (PMID 39628717, 2024). "For example, chronic stress is known to trigger inflammatory responses, disrupt gut microbiota, activate IL-6/STAT3 signaling, and enhance immune responses, including DSS-induced colitis." (PMID 39720595, 2024). "Concurrently, inulin treatment also decreased serum inflammatory markers, such as IL-6 and CALP, prominent indicators of colitis." (PMID 38473746, 2024). "In contrast, the IL-6 concentration reached the highest value in group of TNBS colitis mice fed an HFD with treadmill exercise and the treatment with IAP significantly reduced the plasma IL-6 concentration (p < 0.05)." (PMID 38255781, 2024). "An increasing body of studies has demonstrated that a notable elevation in proinflammatory cytokines, such as IL-6, TNF-α, and IL-1β, constitutes the primary characteristic of colonic injury during the course of colitis development." (PMID 39594091, 2024).
colitis (continued). "MPO, MDA, TNF-α, and IL-6 levels were elevated in the Colitis group but significantly reduced in the DHA-treated group (p < 0.001 for MPO, MDA; p < 0.05 for TNF-α and IL-6)." (PMID 39105785, 2024). "An earlier experiment demonstrated that L. rhamnosus GG Effector Protein HM0539 substantially mitigated inflammation and downregulated IL-6, IL-1β, and TNF-α in murine colitis." (PMID 37639209, 2024). "Increased levels of crucial proinflammatory cytokines, such as IL-6 and IL-1β, were evident in a translational model of DSS-induced colitis in BALB/c mice." (PMID 37695333, 2024). "IL-6/JAK2/STAT3 signaling is a vital axis involved in cell homeostasis and inflammatory signal amplification in various diseases, such as colitis." (PMID 39133435, 2024). "In a murine model of spontaneous colitis, OGR1 perpetuated intestinal inflammation through the expression of IL-6, TNFα, IL-8, and SPARC, a collagen-binding protein that mediates fibrosis, while Ogr1-deficiency was protective." (PMID 38514581, 2024). "Similar to the reported effects of MSCs in chemically-induced colitis, BM-MSC treatments in Winnie mice downregulated the expression of Il6, Ifng, Il1b, Il1a, Tnf, Cxcl2, Tbx21 and Itgam, which were upregulated in Winnie mice and IBD patients." (PMID 38503815, 2024). "ELISA results indicated that DSS-induced colitis mice administered with PSPRS showed higher IL-10 and IgA levels but lower TNF-α, IL-1β, and IL-6 levels." (PMID 38611336, 2024). "IL-6 and TNF-α levels were significantly increased in the colitis group compared to the control group (p < 0.01 and p < 0.05, respectively)." (PMID 39105785, 2024). "Il-6 secretion by IECs is important in innate immune system response to intestinal epithelium insult, particularly in models of DSS-induced colitis." (PMID 39337636, 2024). "In models of colitis, Hericium erinaceus has shown significant downregulation of TNF-α, alongside reductions in IL-6 and IL-1β, reflecting its role in mitigating inflammation similarly to EPA and GLA combinations." (PMID 39597805, 2024). "In several previous studies, it was determined that while spontaneous colitis occurred in IL10−/− mice, the levels of IL-6 were also increased." (PMID 39105785, 2024). "Decrease the severity of DSS-induced colitis and the production of pro-inflammatory cytokines such as tumor necrosis factor (TNF)-α, IL-6, and IL-1β." (PMID 39767818, 2024). "↓ TNF-α, IL-6, CCL2, collagen 3A1, intestinal wall thickness, clinical colitis, tissue damage score, rectal inflammation and bleeding score, mast cell number, and degranulation in the proximal colon." (PMID 39519465, 2024). "The concentrations of proinflammatory cytokines IL-6, IL-1β, and TNF-α significantly increased in the serum of mice with colitis induced with DSS, while the concentration of immunoglobulin IgA in serum was decreased in the DSS group." (PMID 38398846, 2024). "L-theanine suppressed the expression levels of TNF-α, IL-1β, IL-6, iNOS, and COX-2 in DSS-induced colitis, and relieved phosphorylation of GSK-3β and Akt/mTOR in Cd-induced ICR mice." (PMID 39572022, 2024). "Dysregulated IL-6 synthesis can negatively affect autoimmunity and disrupt TGF-β regulation, which protects against colitis." (PMID 39598375, 2024). "Meanwhile, Bacteroides vulgatus can also reduce the expression of colon TNF-α, IL-1β and IL-6 induced by DSS and improve colitis in mice." (PMID 39003416, 2024). "These bacteria suppress the IL-6/STAT3 signaling pathway, thereby reducing the inflammatory response in colitis induced by DSS." (PMID 39338538, 2024). "Curcumin treatment significantly reduced pro-inflammatory cytokines IL-1, IL-6, and CCL-2 in the colon tissue of colitis mice, while increasing anti-inflammatory cytokines IL-33 and IL-10." (PMID 39411430, 2024). "Takahashi found a decreased concentration of serotonin, damage of the myelination, increased tumor necrosis factor-α (TNF-α) and interleukin-6 (IL-6), and depressive-like behavior in DSS-induced colitis." (PMID 38393047, 2024).
colitis (continued). "At the same time, STAT3 knockout also reduced the differences in the expression of IL-6, TNF-α, and IL-1β, as well as ZO-1, occludin, BCL-2, and BAX in the colons of mice with colitis induced by different diets." (PMID 38233383, 2024). "In an in vivo study, Kumujan B inhibited the expression of IL-1β, IL-6, and TNF-α and improved the colon barrier function in dextran sulfate sodium salt (DSS)-induced experimental mice colitis." (PMID 39148547, 2024). "We observed significant increases in colonic IL-6, IL-1β, MCP-1, and TNF-α levels in colitis, which were effectively reduced by CBD and HU308 treatments." (PMID 39682761, 2024). "Studies have shown that icariin can alleviate DSS-induced colitis by inhibiting NF-κB signaling pathway-mediated TNF-α and IL-6 expression." (PMID 38645561, 2024). "Quercetin can alleviate inflammation by reducing the levels of TNF-α, IL-1β, IL-6, and IL-10, thus treating DSS-induced colitis in mice." (PMID 38902425, 2024). "Some research results have shown that the IL-6/STAT3-signaling pathway plays an important role in the occurrence and development of colitis." (PMID 38139367, 2023). "The representative secreted cytokines are IL-1β, IL-6, and TNF-α, and these induce systemic pro-inflammatory responses, including colitis." (PMID 37569708, 2023). "These considerations are further supported by the result that IL-6 reduces STAT3 expression in intestinal epithelial cells (IECs) and increases the severity of DSS-induced colitis in IL-6−/− mice." (PMID 36713833, 2023). "In coptisine chloride therapy for colitis, coptisine chloride significant suppresses mRNA expression, releases of pro-inflammatory cytokines (TNF-α, IFN-γ, IL-1β, IL-6, IL-17) and enhances the mRNA expression level of IL-10, an anti-inflammatory cytokine." (PMID 36859380, 2023). "Recently, Yan-Hong Zhou reported that GBE ameliorates rat inflammatory injury within TNBS-mediated rat colitis models through regulating inflammatory factors (SOD, MDA, TNF-α, NF-κBp65, and IL-6) and antioxidation." (PMID 37111225, 2023). "In comparison to the controls, mice with TNBS colitis and H4R knockout expressed higher levels of chemokines CXCL1 (KC) and CXCL2 (MIP2), IL-6, and the neutrophil enzyme myeloperoxidase (MPO)." (PMID 37373085, 2023). "In line with DSS colitis model results, the secretion of TNF-α, IL-1β, and IL-6, were also obviously reduced in response to LPS when administered with phenolic acids." (PMID 37813835, 2023). "Other cytokines assessed were for the most part unchanged other than IL-6, IL-22, and KC (CXCL1) which were likewise increased in plasma of both C57BL/6 and TCRδ-/- mice with DSS colitis indicative of systemic inflammation." (PMID 37063825, 2023). "On one hand, HEP10 suppressed the production of TNF-α, IL-1β, IL-6, inducible iNOS, and COX-2 in LPS challenged murine macrophage RAW264.7 cells, as well as in colons from DSS-induced colitis mice." (PMID 36771444, 2023). "DPA attenuates inflammation in DSS-induced colitis model; modulates pro-inflammatory cytokines (TNF-α, IL-1β, IL-6) and anti-inflammatory cytokine (IL-10); inhibits synthesis of pro-inflammatory eicosanoids (PGE2, LTB4)." (PMID 37868958, 2023). "It has been reported that naringin inhibits MDSCs, proinflammatory mediators (GM-CSF/M-CSF, IL-6, TNF-ɑ), and the NF-κB/IL-6/STAT3 cascade in colorectal tissue, reducing the severity of colitis and colorectal adenoma." (PMID 36593497, 2023). "In mouse TNBS-induced colitis models, FST administration markedly increased the mice survival rate and decrease plasma IL-6 levels." (PMID 37391444, 2023). "Regarding the APPs’ correlation to mRNA markers, there were moderate positive correlations between CRP levels and Il6, Hif1a, and Il1b1 expression in both trials with DSS-induced colitis." (PMID 37047397, 2023). "Red ginseng fermented with the probiotic L. plantarum decreased IL-6 and TNF-α in the serum and colon tissue and decreased the severity of colitis in DSS-induced colitis mice." (PMID 36986118, 2023).